ITGAM (integrin subunit alpha M)
Description:
Integrin ITGAM/ITGB2 is implicated in various adhesive interactions of monocytes, macrophages and granulocytes as well as in mediating the uptake of complement-coated particles and pathogens. It is identical with CR-3, the receptor for the iC3b fragment of the third complement component. It probably recognizes the R-G-D peptide in C3b. Integrin ITGAM/ITGB2 is also a receptor for fibrinogen and factor X. It recognizes P1 and P2 peptides of fibrinogen gamma chain. Regulates neutrophil migration. In association with beta subunit ITGB2/CD18, required for CD177-PRTN3-mediated activation of TNF primed neutrophils. Integrin ITGAM/ITGB2 is also a receptor for ICAM1 ligand ensuring adhesion between stimulated neutrophils and stimulated endothelial cells. May regulate phagocytosis-induced apoptosis in extravasated neutrophils (By similarity). May play a role in mast cell development (By similarity). Required with TYROBP/DAP12 in microglia to control production of microglial superoxide ions which promote the neuronal apoptosis that occurs during brain development (By similarity).
Synonyms: CD11b; CR3A; HNA-4; MAC-1; MAC1A; MO1A; SLEB6
Tractability: Small molecule: a structure with a bound ligand is known; a high-quality ligand is known. Antibody: a drug acting on it is in phase 2 or 3 trials; UniProt places it where antibodies can reach, with high confidence; its Gene Ontology location is reachable by antibodies, with high confidence; UniProt predicts a signal peptide or a membrane-spanning region. PROTAC: its protein half-life has been measured; a small molecule that binds it is known.
Target class: Membrane receptor
Gene: Protein-coding gene on chromosome 16 (31,259,967 to 31,332,892, forward strand). Ensembl gene ENSG00000169896.
Subcellular location: Cell membrane; Membrane raft
Pathways (Reactome):
Immune System: Interleukin-4 and Interleukin-13 signaling; Neutrophil degranulation; Toll Like Receptor 4 (TLR4) Cascade
Extracellular matrix organization: Integrin cell surface interactions
Hemostasis: Cell surface interactions at the vascular wall
Gene Ontology:
Molecular function: cell adhesion receptor activity; heat shock protein binding; protein binding; amyloid-beta binding; cargo receptor activity; complement component C3b binding; integrin binding; signaling receptor activity; protein-containing complex binding
Biological process: cell-cell adhesion mediated by integrin; cell-matrix adhesion; ectodermal cell differentiation; leukocyte adhesion to vascular endothelial cell; positive regulation of neutrophil degranulation; positive regulation of superoxide anion generation; amyloid-beta clearance; cell adhesion; cell-cell adhesion; complement receptor mediated signaling pathway; complement-mediated synapse pruning; forebrain development; integrin-mediated signaling pathway; microglial cell activation; negative regulation of dopamine metabolic process; phagocytosis, engulfment; positive regulation of microglial cell mediated cytotoxicity; positive regulation of protein targeting to membrane; receptor-mediated endocytosis; vertebrate eye-specific patterning; heterotypic cell-cell adhesion; leukocyte cell-cell adhesion; response to amphetamine; response to curcumin; response to estradiol; and 3 more
Cellular component: cell surface; extracellular exosome; extracellular region; integrin alphaM-beta2 complex; membrane raft; plasma membrane; plasma membrane raft; external side of plasma membrane; integrin complex; specific granule membrane; tertiary granule membrane
Genetic constraint (gnomAD): Loss-of-function variants: 69 observed, 124.34 expected, observed/expected ratio (o/e) 0.55, 90% interval 0.46 to 0.68. The upper end of that interval is the gene's LOEUF score, 0.68, which puts it in group 2 of 6, group 1 being the genes least tolerant of losing a copy. Missense variants: 1,287 observed, 1,426.3 expected, observed/expected ratio (o/e) 0.9, 90% interval 0.86 to 0.94. Synonymous variants: 565 observed, 574.1 expected, observed/expected ratio (o/e) 0.98, 90% interval 0.92 to 1.05.
Homologues: Orthologues: chimpanzee ITGAM (99% identical), macaque ITGAM (93% identical), pig ITGAM (79% identical), rabbit ITGAM (77% identical), dog ITGAM (76% identical), rat Itgad (74% identical), mouse Itgam (74% identical), guinea pig ITGAM (72% identical), Drosophila melanogaster mew (22% identical), Caenorhabditis elegans ina-1 (20% identical), Drosophila melanogaster if (20% identical), Caenorhabditis elegans pat-2 (19% identical), and 3 more. Paralogues in human: ITGAX (61% identical), ITGAD (59% identical), ITGAL (31% identical), ITGAE (29% identical), ITGA10 (28% identical), ITGA11 (28% identical), ITGA1 (27% identical), ITGA2 (27% identical), ITGA4 (21% identical), ITGA9 (21% identical), ITGAV (21% identical), ITGA5 (20% identical), and 5 more.
Diseases named in the same sentence as ITGAM in open-access papers:
ITGAM is named in the same sentence as 573 diseases in open-access papers, as found by Europe PMC text mining. Sharing a sentence is not in itself a finding about the gene and the disease. The quoted sentences say what the papers report.
breast cancer (147 papers, 2009 to 2026). A primary or metastatic malignant neoplasm involving the breast. "One study investigating biomarkers in breast cancer brain metastasis via integrated genomic and epigenomic analysis showed that hypermethylation and downregulation of ITGAM were associated with defects in cell migration and adhesion." (PMID 33104706, 2020). "Unexpectedly, ezrin is essential for the basal and breast cancer cell-stimulated THP-1 expression of ITGAM mRNA that encodes integrin CD11b, critical for cell adhesion." (PMID 33086476, 2020). "Of these genes, ITGAM was the most significantly correlated with LCK in all subtypes of breast cancer, with the highest correlation occurring in TNBC." (PMID 37686072, 2023). "Of these genes, ITGAM is the most heavily correlated with LCK in all subtypes of breast cancer, with the highest correlation occurring in TNBC." (PMID 37686072, 2023). "Co-culture of macrophages with CM from both breast cancer cell lines markedly enhanced ITGAM mRNA expression; the stimulation by CM from the more aggressive MDA-MB-231 cells was about twice that by MCF-7 CM." (PMID 33086476, 2020). "ITGAM and ITGAX are mainly involved in systemic lupus erythematosus, while TYEOBP and C3AR1 have been studied in the context of breast cancer." (PMID 31740624, 2019).
melanoma (137 papers, 2011 to 2026). A malignant, usually aggressive tumor composed of atypical, neoplastic melanocytes. "In metastases from melanoma patients, high levels of miR-146a, miR-155, miR-125b, miR-100, let7e, miR-125a, miR-146b, and miR-99b were detected and correlated with CD163, CD14, CD209, CD68, ITGAM, and CD33 myeloid markers." (PMID 32793228, 2020). "Our results suggested that TNF receptors, MHC molecules, ITGAM, CD247 or CD14 leading gene sets can preciously distinguish the responders for non-responders in patients with melanoma that received ICB therapies." (PMID 34238310, 2021). "CD14, ITGAM, CD247 and MHC molecules not only significantly dysregulated between the responders and non-responders of patients with melanoma but also presented accuracy prediction of immunotherapy response." (PMID 34238310, 2021).
Sepsis (132 papers, 2008 to 2026). Sepsis is defined as life-threatening organ dysfunction caused by a dysregulated host response to infection. "For instance, ITGAM is crucial for leukocyte adhesion and migration, and its upregulation has been associated with enhanced inflammatory responses in sepsis." (PMID 41259376, 2025). "Existing studies have indicated that ITGAM modulates the cardiac immune microenvironment in models of sepsis-induced cardiomyopathy, either suppressing or enhancing inflammatory responses depending on the disease stage." (PMID 41358004, 2025). "Among them, the AUCs of ITGAM, KIF1B, RRAGD, S100A9, SCOC, and SPTLC2 in the internal and external test sets were more than 0.6, indicating diagnostic significance for sepsis." (PMID 37834169, 2023). "In fact, in one recent study, using a four-gene signature that includes ITGAM and three other genes has demonstrated a promising model to diagnose patients with sepsis." (PMID 36900096, 2023). "Another study found that ITGAM also plays an important role in methicillin-resistant Staphylococcus aureus (MRSA)-induced sepsis." (PMID 36119022, 2022). "Based on the results of PPI network and hub gene extraction, ITGAM interacts with other genes to the strongest extent, and is probably the most important gene between COVID-19 and sepsis." (PMID 36119022, 2022). "A previous study had revealed that ITGAM mainly contributed to the progression of sepsis by promoting the nuclear, cytoplasmic translocation and activating release of HMGB1." (PMID 33949285, 2021). "Collectively, these findings indicate that dysregulation of the GM may facilitate the activation of NETs, while the expression of integrins ITGAM and ITGB2 is closely linked to the progression of sepsis-induced ALI." (PMID 41586375, 2025). "Understanding the precise mechanisms by which ITGAM mediates leukocyte adhesion and migration could provide insights into potential therapeutic targets for modulating immune responses in sepsis." (PMID 41259376, 2025). "The results suggested that the expressions of LCK and CCL5 were significantly higher in normal samples than in samples from patients with sepsis, while the expressions of ITGAM and MMP9 were significantly lower in normal samples than in samples from patients with sepsis in the GSE57065 dataset." (PMID 35184762, 2022). "Additionally, a different research discovered that ITGAM also has a significant impact on sepsis caused by methicillin-resistant Staphylococcus aureus (MRSA).After being infected with MRSA, the mortality rate of ITGAM knockout mice was considerably greater compared to that of control mice." (PMID 38678059, 2024). "The ROC curve analysis revealed that ITGAM, CXCR2, and FCGR3B exhibited high classification accuracy (AUC >0.9) between the Sepsis and Control groups, indicating their strong potential for early diagnosis." (PMID 41259376, 2025). "Collectively, these findings indicate that sepsis induces robust NET formation, while the GM modulates the expression of ITGAM and ITGB2, thereby preserving endothelial structure and barrier integrity in the presence of NETs." (PMID 41586375, 2025). "CLP-induced sepsis triggered severe pulmonary edema, neutrophil infiltration, and NET accumulation, alongside downregulation of ITGAM/ITGB2 and tight junction proteins (β-catenin/ZO-1/VE-cadherin)." (PMID 41586375, 2025). "Receiver operating characteristic (ROC) curve analysis demonstrated that ITGAM, CXCR2, and FCGR3B exhibited extremely high accuracy in distinguishing sepsis from controls (with an area under the curve greater than 0.9)." (PMID 41259376, 2025). "In conclusion, our study reveals a novel mechanism whereby gut dysbiosis exacerbates sepsis-induced ALI by promoting NET formation and downregulating ITGAM and ITGB2, leading to compromised pulmonary endothelial barrier function." (PMID 41586375, 2025).
Sepsis (continued). "We unveil a novel gut microbiota-NET-integrin axis in sepsis-induced ALI, where microbial dysbiosis promotes NET-mediated suppression of ITGAM/ITGB2, leading to endothelial barrier failure." (PMID 41586375, 2025). "Studies have found that core genes ITGAM and C3AR1 are expressed at higher levels in the plasma of sepsis patients, and through clinical translation, they can become new targets for the diagnosis and treatment of sepsis." (PMID 41209006, 2025). "The results indicated that ITGAM, CD44, C3AR1, and IL2RG exhibited significantly higher expression in the sepsis group compared to the SIRS group." (PMID 38678059, 2024). "Against this backdrop, the present study investigates whether GM dysbiosis exacerbates sepsis-induced ALI by promoting NET formation and suppressing the expression of the integrins ITGAM and ITGB2, thereby disrupting pulmonary endothelial barrier integrity." (PMID 41586375, 2025). "Next, the ROC curves show that the ITGAM, CXCR2, and FCGR3B expression levels provide high accuracy for classifying the Sepsis and Control group (AUC > 0.9); MMP9, MPO, and CTSG expression levels exhibit moderate accuracy for this classification (0.7 < AUC < 0.9)." (PMID 41259376, 2025). "Furthermore, a meta-analysis identified four genes, namely ITGAM, CD44, C3AR1, and IL2RG, which were highly expressed in the sepsis group compared to the normal group (P < 0.05)." (PMID 38678059, 2024). "Importantly, ITGAM and ITGB2 may emerge as promising therapeutic targets for mitigating sepsis-induced ALI, while microbiota-based interventions such as FMT offer translational potential as adjunctive therapeutic strategies." (PMID 41586375, 2025). "This network uncovered regulatory interactions among genes like MPO, CXCR2, ITGAM, SPI1, SPI1 and EP300, suggesting these TFs may participate in sepsis-related immune responses and inflammatory regulation by modulating the transcriptional activity of core genes." (PMID 41259376, 2025). "Finally, we identified a four-gene signature, containing the hub genes LCK, CCL5, ITGAM, and MMP9, and established a model that could be used to diagnose patients with sepsis." (PMID 35184762, 2022).
glioma (124 papers, 2010 to 2025). A benign or malignant brain and spinal cord tumor that arises from glial cells (astrocytes, oligodendrocytes, ependymal cells). "By combining CDCP1, CD44 and ITGAM, a prognostic risk model was established and validated to predict 1-year, 3-year, and 5-year survival in glioma patients." (PMID 35410293, 2022). "The risk model (considering CDCP1 combined with CD44 and ITGAM expression) could represent a tool for predicting survival and prognosis in glioma patients." (PMID 35410293, 2022). "The Spearman correlation analysis results suggested that the immune marker sets of Treg (FOXP3, CCR8, TGFβ1), TAM (CCL2, CD68, IL-10), and MDSC (CD33, ITGAM, FUT4) were significantly associated with the PROS1 expression in glioma." (PMID 36685506, 2022). "We established a risk model (which considered the expression of CDCP1 combined with CD44 and ITGAM) and verified that it can be used to predict prognosis in glioma/GBM." (PMID 35410293, 2022). "The identification of the downstream signals of HK2 demonstrated that the high expression of hub genes, including ITGB2, CD53, C3AR1, CYBB and ITGAM, maybe a potential target for the treatment of glioma." (PMID 35982398, 2022). "Ultimately, we speculate that CDCP1, CD44 and ITGAM can be used to better diagnose glioma and predict the prognosis of glioma patients." (PMID 35410293, 2022).
leukemia (88 papers, 2011 to 2026). A malignant (clonal) hematologic disorder, involving hematopoietic stem cells and characterized by the presence of primitive or atypical myeloid or lymphoid cells in the bone marrow and the blood. "The non-leukemic nature of the three monocyte/macrophage clusters was confirmed by low expression of leukemia myeloid markers (ITGAM, ANPEP, CD33)." (PMID 37798266, 2023). "The ITGAM also plays an important role in the tumor microenvironment in leukemia cell activation, chemotaxis, and cytotoxicity." (PMID 35280440, 2022). "As a major surface antigen family on human leukocyte family member, previous studies have reported the key role of ITGAM in the development and prognosis of human leukemia, ovarian cancer, and colorectal cancer." (PMID 32509861, 2020). "ITGAM is involved in the bone marrow differentiation and lysine specific demethylase-1 (LSD-1) activity, which contributes to the immune escape from leukemia cells." (PMID 35280440, 2022). "ITGAM may participate in the pathogenesis of AML through AML related gene methylation and increase the immune escape of leukemia cells." (PMID 34148032, 2021).
Stroke (87 papers, 2012 to 2025). Sudden impairment of blood flow to a part of the brain due to occlusion or rupture of an artery to the brain. "In summary, these results suggest that ITGAM is associated with brain cell apoptosis, correlated to stroke severity and unfavorable functional outcomes." (PMID 40297585, 2025). "We further investigated the diagnostic value of ITGAM to distinguish early- from late-onset stroke patients." (PMID 40297585, 2025). "Zhao reported that ITGAM is a potential diagnostic and prognostic biomarker of unstable atherosclerotic plaque-related stroke, which will be a novel therapeutic target and the development of novel management strategies." (PMID 37179331, 2023). "Correlating with clinical features, the expression levels of ITGAM are positively associated with the severity of the stroke, poorer functional outcome, and the extent of infarction, drawing our attention to the potential of has-miR-3646-ITGAM as a therapeutic target for IS." (PMID 40297585, 2025). "As part of the integrin family, ITGAM may be implicated in post-stroke inflammatory responses, including promoting leukocyte adhesion and migration, thereby exacerbating brain tissue damage." (PMID 40297585, 2025). "In addition, ROC curve analysis reflected the good performance of ITGAM as a potential biomarker for the diagnosis of IS and for differentiating between early- and late-onset stroke." (PMID 40297585, 2025). "In the CCS3 subgroup, 3 individual proteins, CA3, ITGAM (integrin subunit αM), and TAGLN2 (AUC=0.72, 0.72, and 0.7183, respectively), were predictive of recurrent stroke." (PMID 38420847, 2024).